TRPC6 (transient receptor potential cation channel subfamily C member 6)
Diseases named in the same sentence as TRPC6 in open-access papers (continued):
Sharing a sentence is not in itself a finding about the gene and the disease.
lung fibrosis (6 papers, 2019 to 2026). "TRPC6 (transient receptor potential cation channels; canonical subfamily C, member 6) is widespread localized in mammalian tissues like kidney and lung and associated with progressive proteinuria and pathophysiological pulmonary alterations, e.g., reperfusion edema or lung fibrosis." (PMID 33805686, 2021). "We were able to demonstrate an up-regulation of TRPC6 channels in murine lung fibroblasts after the application of TGF-β1, similar to cardiac fibroblasts, and TRPC6−/− mice were partially protected from bleomycin-induced lung fibrosis." (PMID 36139480, 2022). "TRPC6 mediated Ca2+ influx induces CnA/NFAT activation that is necessary in the progression of pulmonary fibrosis and myofibroblast transformation." (PMID 32719603, 2020). "Only tissue specific TRP-deficiency will answer the question which cells apart from fibroblasts are responsible for the development of lung fibrosis due to TRPC6 or TRPV4 function." (PMID 30717260, 2019). "Deficiencies of TRPC6 and TRPV4 independently protected lungs in a mouse model of bleomycin-induced lung fibrosis." (PMID 30717260, 2019). "Metformin administration and manipulation of TRPC6 channels may be a therapeutic target for the treatment of pulmonary fibrosis." (PMID 41810646, 2026). "Thus, TRPA1 activity seems to inhibit fibroblast-to-myofibroblast differentiation, a hallmark of lung fibrosis development in clear contrast to TRPV4 and TRPC6 channels, which support fibrotic processes." (PMID 36139480, 2022). "In addition, TRPC6 has also been shown to contribute to the development of experimental pulmonary fibrosis, myofibroblast transdifferentiation and wound healing." (PMID 32719603, 2020). "This review will focus on TRP channels (TRPA1, TRPC6, TRPV1, and TRPV4), predominantly expressed in non-neuronal lung tissues and their involvement in pathways associated with diseases like asthma, cystic fibrosis, chronic obstructive pulmonary disease (COPD), lung fibrosis, and edema formation." (PMID 30717260, 2019).
Arrhythmia (5 papers, 2017 to 2023). Any cardiac rhythm other than the normal sinus rhythm. "Herein, our present study provides the first evidence that links hyperforin and TRPC6 activation to the enhanced susceptibility to arrhythmias." (PMID 30618800, 2018). "Mutations in TRPC6 have also been associated with cardiac arrhythmias which could, if present, disrupt heart regeneration at later stages." (PMID 38259319, 2023). "We observed that perfusion with hyperforin could increase the arrhythmia score in ex vivo hearts, implying a possible arrhythmogenic role of SOCE/TRPC6 in the whole heart setting." (PMID 30618800, 2018).
autism (5 papers, 2022 to 2025). Persistent deficits in social interaction and communication and interaction as well as a markedly restricted repertoire of activity and interest as well as repetitive patterns of behavior. "TRPC6 mutations in ASD individuals are genetic risk factors for ASD and TRPC6 KD causes the autism-like hyperactivity behavior in Drosophila." (PMID 37552395, 2023). "Loss-of-function mutations in TRPC6 reduce calcium influx in human pluripotent stem cell (hPSC)–derived neurons and TRPC6 knockdown (KD) in Drosophila causes autism-like behavioral deficits and leads to a hyperactivity phenotype." (PMID 37552395, 2023). "In addition, it was revealed that circCdh9 was also significantly downregulated in the cerebellum and upregulated in the prefrontal cortex and the amygdala of autism animal models, while both CDH9 and TRPC6 genes have been implicated in autism pathogenesis in humans." (PMID 40868063, 2025).
autism spectrum disorder (5 papers, 2020 to 2025). A spectrum of developmental disorders that includes autism, and Asperger syndrome. "TRPC6 variants (i.e., loss-of-function mutations) are candidate risk genes for Autism Spectrum Disorder (ASD); TRPC6-mediate neuronal SOCE has been demonstrated in a human iPS model to be crucial in counteracting neuronal hyperexcitability in ASD." (PMID 40498020, 2025). "High-throughput sequencing based on TRPC6 in autism spectrum disorder (ASD) patients and controls revealed the presence of more non-synonymous mutations in ASD individuals, suggesting that TRPC6 may carry out as a potential predisposing factor for ASD." (PMID 32256338, 2020).
cardiomyopathy (5 papers, 2016 to 2025). A disease of the heart muscle or myocardium proper. "We found that female B6.129 wild-type and Trpc6-deficient mice were far less susceptible to doxorubicin-induced cardiac damage and cardiomyopathy than males." (PMID 35096991, 2021). "Although female wild-type and Trpc6-deficient mice were less susceptible to doxorubicin-induced cardiac damage and cardiomyopathy, we did observe other significant effects of Trpc6 deficiency in female mice compared to males." (PMID 35096991, 2021). "In male mice in this study, we found that Trpc6 deficiency improved doxorubicin-induced cardiac damage (vacuolation, fibrosis, Tnni3 and Myh7) and cardiomyopathy indicating that Trpc6 promotes cardiac damage associated with doxorubicin therapy." (PMID 35096991, 2021). "Next, we sought to prevent cardiomyopathy caused by doxorubicin using GsMTx-4 in an animal model and found blocking TRPC6 in vivo significantly improved cardiac remodeling/fibrosis and dysfunction caused by doxorubicin." (PMID 32903434, 2020). "Further work is needed to assess the functional consequences of the associated genetic variants and to elucidate the molecular mechanism of TRPC6 relative to doxorubicin-induced cardiomyopathy and HF in general." (PMID 32903434, 2020). "In this study, we hypothesized that genetic deficiency of Trpc6 would decrease cardiotoxicity and cardiomyopathy in male and female mice given doxorubicin." (PMID 35096991, 2021). "In a mice model of DIC, TRPC6 deficiency provides cardioprotection against doxorubicin-induced cardiac damage and cardiomyopathy in male mice, highlighting that TRPC6 plays a critical role in promoting cardiac toxicity during chemotherapy." (PMID 40362211, 2025). "In this study, we specifically tested the role of Trpc6 in doxorubicin-induced cardiotoxicity and cardiomyopathy using male and female Trpc6 whole body knockout mice." (PMID 35096991, 2021). "In vitro and in vivo, Trpc6 inhibition with the peptide GsMTx4 reduced doxorubicin-induced cardiotoxicity and cardiomyopathy in male mice." (PMID 35096991, 2021). "Trpc6 induces cardiac damage and cardiomyopathy following treatment with doxorubicin in male mice and may be a therapeutic target for cardioprotection in patients." (PMID 35096991, 2021). "We are also the first study to our knowledge to examine whether sex differences exist in the effect of Trpc6 on cardiomyopathy following doxorubicin therapy." (PMID 35096991, 2021). "TRPC6 knock-down or knock-out animal models will be required to demonstrate that inhibition of TRPC6 alone prevents or reduces doxorubicin-induced cardiotoxicity and cardiomyopathy." (PMID 32903434, 2020). "Doxorubicin-induced apoptosis and cardiomyopathy was modeled in human iPSC-derived cardiomyocytes and endothelial cells and a mouse model, respectively, that were pre-treated with GsMTx-4, an inhibitor of TRPC6." (PMID 32903434, 2020). "Importantly, blocking TRPC6 in vitro and in vivo reduced doxorubicin-mediated toxicity and cardiomyopathy further suggesting that inhibition of TRPC6 may have potential as a cardioprotective therapy." (PMID 32903434, 2020). "Thus overall, Trpc6 appears to increase cardiac damage in response to doxorubicin in females but not severely enough to lead to cardiomyopathy at the dose used in these experiments." (PMID 35096991, 2021).
chronic obstructive pulmonary disease (5 papers, 2018 to 2023). A chronic and progressive lung disorder characterized by the loss of elasticity of the bronchial tree and the air sacs, destruction of the air sacs wall, thickening of the bronchial wall, and mucous accumulation in the bronchial tree. "Chronically stimulated lung macrophages from patients with chronic obstructive pulmonary disease (COPD) express TRPC6 at high levels." (PMID 29973568, 2018).
endothelial dysfunction (5 papers, 2019 to 2026). In vascular diseases, endothelial dysfunction is a systemic pathological state of the endothelium (the inner lining of blood vessels) and can be broadly defined as an imbalance between vasodilating and vasoconstricting substances produced by (or acting on) the endothelium. "We have reported that mTBI closed-head mild TBI causes long-lasting systemic endothelial dysfunction, which is resolved between 7- and 21-day post-injury, in mice by overacting TRPC6 channels." (PMID 35203995, 2022). "We show for the first time that TRPC6 genetic ablation or pharmacological inhibition with larixyl acetate prevents TBI-associated systemic endothelial dysfunction in mice." (PMID 30704505, 2019). "We found that TRPC6 activation may underlie the development of this systemic endothelial dysfunction after TBI." (PMID 30704505, 2019). "Therefore, we next tested whether larixyl-mediated inhibition of TRPC6 activity in vivo would be efficacious at reducing TBI-associated endothelial dysfunction in 129S-C57BL/6-F2 and C57BL/6 mice subjected to TBI and treated with larixyl acetate." (PMID 30704505, 2019). "Our previous study indicated that the endothelial dysfunction induced by TBI might be due to the overacting of TRPC6 channels, which could be activated by some increased levels of chemokine through TLR4." (PMID 35203995, 2022). "Furthermore, we established that larixyl acetate, an inhibitor of TRPC6, is effective in preventing TBI-associated systemic endothelial dysfunction when it was administered intraperitoneally for 7 days following TBI." (PMID 30704505, 2019). "Since TRPC6 knockout mice exhibited no TBI-associated endothelial dysfunction, we next tested whether pharmacological inhibition of the channel would show any therapeutic potential." (PMID 30704505, 2019). "We hypothesize that TRPC1, TRPC3, TRPC4, and TRPC6 act as critical molecular effectors mediating hypoxia-driven calcium influx and downstream signaling pathways that lead to pulmonary vascular remodeling, endothelial dysfunction, and increased pulmonary arterial pressure." (PMID 41751997, 2026). "However, given that TRPC6 is more highly expressed in vascular tissue than in the heart, (an important consideration for functional validation) and doxorubicin cardiotoxicity may also be mediated through endothelial dysfunction, we also performed the experiment in human endothelial cells." (PMID 32903434, 2020). "Lipopolysaccharide treatment in vitro failed to elicit endothelial dysfunction in TRPC6 knockout mice." (PMID 30704505, 2019).
liver fibrosis (5 papers, 2022 to 2024). "To conclude, the upregulation of TRPM7, TRPM8, TRPV3, TRPV4, and TRPC6 is significantly associated with the onset and progression of liver fibrosis." (PMID 37569884, 2023). "In the context of liver fibrosis, the upregulation of TRPC6, TRPV3, TRPV4, and TRPM7 channels promotes the activation of HSCs and the production and accumulation of ECM components, including α-SMA and COL1A1." (PMID 37569884, 2023). "Taken together, hypoxia-induced TRPC6 activation leads to ECM protein deposition, which promotes the formation of liver fibrosis." (PMID 36187789, 2022).
triple-negative breast carcinoma (5 papers, 2018 to 2023). An invasive breast carcinoma which is negative for expression of estrogen receptor (ER), progesterone receptor (PR), and human epidermal growth factor receptor 2 (HER2). "The mechanism underlying hyperactivation of Orai and TRPC6 channels in triple negative breast cancer cells deserves further investigation." (PMID 33916304, 2021). "Thus, interfering with Furin activity-mediated Ca2+ mobilization and Orai and TRPC6 activation represent a potential strategy controlling malignant phenotype and resistance to therapy in triple negative breast cancer cells." (PMID 33916304, 2021). "Therefore, our observations reveal that TRPC6 is essential for ER+ and triple negative breast cancer cell proliferation." (PMID 30223530, 2018). "As reported in normal and tumor breast tissues, we have found that TRPC6 expression is enhanced in ER+ and triple negative breast cancer cell lines as compared to non-tumoral breast cells." (PMID 30223530, 2018). "Here we show that the estrogen receptor positive and triple negative breast cancer cell lines, MCF7 and MDA-MB-231, respectively, exhibit enhanced expression of the TRPC6 channel as compared to the non-tumoral MCF10A cell line." (PMID 30223530, 2018).
dementia (4 papers, 2015 to 2023). Loss of intellectual abilities interfering with an individual's social and occupational functions. "Activation of TRPC6 with hyperforin could delay the present of dementia caused by RH." (PMID 35077394, 2022). "Furthermore, a positive correlation between TRPC6 mRNA blood levels and mini-mental-state-examination scores, and an inverse correlation between TRPC6 mRNA blood levels, clinical dementia ratings scores, and index for activities of daily living (ADL) scores, were reported in AD patients." (PMID 37240413, 2023).
esophageal squamous cell carcinoma (4 papers, 2011 to 2024). Esophageal squamous cell carcinoma (ESCC) is a type of esophageal carcinoma (EC) that can affect any part of the esophagus, but is usually located in the upper or middle third. "Moreover, the TRPC6 channel was blocked when esophageal squamous cell carcinoma cells were injected into nude mice, and the tumorigenicity was reduced." (PMID 35392906, 2022). "The TRPC6 channel, which is essential for cell proliferation and cell cycle, is highly expressed in esophageal squamous cell carcinoma (ESCC) and renal cell carcinoma (RCC)." (PMID 38734935, 2024).
head and neck squamous cell carcinoma (4 papers, 2013 to 2020). A squamous cell carcinoma that arises from any of the following anatomic sites: lip and oral cavity, nasal cavity, paranasal sinuses, pharynx, larynx, and salivary glands. "TRPC6, on the other hand, promotes cancer cell migration in head and neck squamous cell carcinomas and in glioblastoma." (PMID 32350291, 2020). "In fact TRPC6 expression is increased in head and neck squamous cell carcinomas tumor samples and cancer cell lines." (PMID 24204345, 2013). "In human head and neck squamous cell carcinomas (HNSCC), TRPC6 was overexpressed, and knock-down of TRPC6 in HNSCC potently attenuated invasion." (PMID 32138386, 2020).
kidney injury (4 papers, 2020 to 2023). Trauma to the kidney. "One limitation of our study is that global KO of TRPC6 may impact several cell types that normally express TRPC6, which may contribute to BP regulation and the development of kidney injury." (PMID 34866402, 2022). "Taken together, these data unveil a novel mechanism involving κ-ORs and TRPC6 in regulation of [Ca2+]i homeostasis that could be pharmacologically targeted to abate the development of kidney injury during opioid treatment." (PMID 33046522, 2020).
lung carcinoma (4 papers, 2013 to 2018). "TRPC6 also has been linked to lung cancer: inhibition of TRPC6 channels lowers the intracellular Ca2+ concentration in A549 cells and strongly reduces the invasion of A549 cells." (PMID 29772843, 2018). "The present study, for the first time, show that inhibition of TRPC6 reduces the invasion of A549 lung cancer cells possibly associated with decreased expression of fibronectin and ZO-1." (PMID 28030826, 2017). "Using isoform-specific blocking antibodies, we found that the blockade of TRPC1, TRPC4 and TRPC6 channels causes a significant inhibition of A549 cell proliferation, suggesting that TRPC1, TRPC4 and TRPC6 are important for lung cancer cell proliferation." (PMID 23840757, 2013). "In this study, we have shown that TRPC1, TRPC3, TRPC4 and TRPC6 exist in human lung cancer including the adenocarcinoma, squamous cell carcinoma and the adenocarcinoma-derived cell line A549." (PMID 23840757, 2013). "However, for the first time, we show that TRPC6 modulates intracellular Ca2+ in A549 lung cancer cells and therefore controls cell cycle progression and that TRPC6 is highly expressed in NSCLC cells at the S-G2/M phase rather than at the G1 phase." (PMID 28030826, 2017). "Linear multivariance regression analysis also showed a negative correlation of the mRNA expression of TRPC1, TRPC3, TRPC4 and TRPC6 to lung cancer differentiation grade with standardized β coefficient sequence of TRPC1 (−0.563)>TRPC4 (−0.360) >TRPC6 (+0.271) and TRPC3 (−0.057), respectively." (PMID 23840757, 2013). "In conclusion, we found that TRPC1, TRPC3, TRPC4 and TRPC6 channels are expressed in lung cancer." (PMID 23840757, 2013). "However, it remains unclear whether TRPC6 is critical for cell cycle progression and metastasis of lung cancer cells." (PMID 28030826, 2017). "In other words, enhanced TRPC6 expression may be critical for lung cancer cell cycle progression." (PMID 28030826, 2017). "On the contrary, over-expression of TRPC1 and TRPC6 increased the A549 proliferation, however the effect of overexpression of TRPC3 and TRPC4 has not achieved significance in the lung cancer cells." (PMID 23840757, 2013).
ovarian carcinoma (4 papers, 2013 to 2025). A malignant neoplasm originating from the surface ovarian epithelium. "For example, TRPC1, TRPC3 and TRPC6 were proven to be participated in proliferation of multiple types of cancer, including breast caner, ovarian cancer, liver cancer, and brain cancer." (PMID 29463225, 2018).
pancreatic cancer (4 papers, 2011 to 2022). "Similarly, the CXCR2-dependent recruitment of neutrophil granulocytes to the stroma of pancreatic cancer where they elicit high immunosuppressive activity and drive disease progression could potentially be targeted by TRPC6 blockers." (PMID 31950205, 2020).